THORLNC (testis associated oncogenic lncRNA)
Synonyms: THOR; LOC124907879
Gene: Long non-coding RNA gene on chromosome 2 (118,124,351 to 118,224,018, reverse strand). Ensembl gene ENSG00000226856.
Diseases named in the same sentence as THORLNC in open-access papers:
THORLNC is named in the same sentence as 23 diseases in open-access papers, as found by Europe PMC text mining. Sharing a sentence is not in itself a finding about the gene and the disease.
THORLNC shares sentences with these, for which no sentence is quoted: cancer (21 papers); tumor (11); osteosarcoma (9); gastric cancer (6); melanoma (5); renal cell carcinoma (5); glioma (4); nasopharyngeal carcinoma (4); retinoblastoma (3); colorectal cancer (2); hepatocellular carcinoma (2); lung carcinoma (2); non-small cell lung carcinoma (2); ovarian carcinoma (2); breast carcinoma (1); colon cancer (1); endometrial cancer (1); liver cancer (1); non-small cell lung adenocarcinoma (1); prostate carcinoma (1); renal carcinoma (1); tongue squamous cell carcinoma (1); triple-negative breast carcinoma (1).